EIF4G3 (eukaryotic translation initiation factor 4 gamma 3)
Description:
Component of the protein complex eIF4F, which is involved in the recognition of the mRNA cap, ATP-dependent unwinding of 5'-terminal secondary structure and recruitment of mRNA to the ribosome. Functional homolog of EIF4G1.
Synonyms: eIF-4G 3; eIF4G 3; eIF4GII
Tractability: PROTAC: ubiquitination databases record sites on it; its protein half-life has been measured.
Gene: Protein-coding gene on chromosome 1 (20,806,292 to 21,177,285, reverse strand). Ensembl gene ENSG00000075151.
Subcellular location (Human Protein Atlas): Cytosol
Pathways (Reactome):
Disease: Dengue Virus Genome Translation and Replication
Immune System: ISG15 antiviral mechanism
Gene Ontology:
Molecular function: RNA binding; RNA cap binding; translation factor activity, RNA binding; translation initiation factor activity
Biological process: negative regulation of autophagy; positive regulation of translation; regulation of translational initiation; spermatid development; translational initiation
Cellular component: cytoplasm; cytosol; eukaryotic translation initiation factor 4F complex
Genetic constraint (gnomAD): Loss-of-function variants: 22 observed, 147.66 expected, observed/expected ratio (o/e) 0.15, 90% interval 0.1 to 0.21. The upper end of that interval is the gene's LOEUF score, 0.21, which puts it in group 1 of 6, group 1 being the genes least tolerant of losing a copy. Missense variants: 1,407 observed, 1,824.6 expected, observed/expected ratio (o/e) 0.77, 90% interval 0.74 to 0.81. Synonymous variants: 627 observed, 649.31 expected, observed/expected ratio (o/e) 0.97, 90% interval 0.9 to 1.03.
Homologues: Orthologues: macaque EIF4G3 (97% identical), chimpanzee EIF4G3 (96% identical), rabbit EIF4G3 (92% identical), pig EIF4G3 (91% identical), dog EIF4G3 (90% identical), guinea pig EIF4G3 (88% identical), rat Eif4g3 (85% identical), mouse Eif4g3 (84% identical), tropical clawed frog eif4g3 (69% identical), zebrafish eif4g3b (57% identical), zebrafish eif4g3a (55% identical). Paralogues in human: EIF4G1 (46% identical), EIF4G2 (16% identical).
Diseases named in the same sentence as EIF4G3 in open-access papers:
EIF4G3 is named in the same sentence as 28 diseases in open-access papers, as found by Europe PMC text mining. Sharing a sentence is not in itself a finding about the gene and the disease. The quoted sentences say what the papers report.
glioma (3 papers, 2019 to 2023). A benign or malignant brain and spinal cord tumor that arises from glial cells (astrocytes, oligodendrocytes, ependymal cells). "These analyses reveal indeed that the expression of EIF4G1 and EIF4G2 is significantly increased in gliomas whereas EIF4G3 is decreased in gliomas and all GBM subtypes." (PMID 31795417, 2019).
lung squamous cell carcinomas (3 papers, 2021 to 2022). "Another preclinical study reported the synergistic effect of tucidinostat and radiotherapy in inducing cell apoptosis and suppressing cancer stemness through regulating mir375- Eukaryotic translation initiation factor 4 gamma 3 (EIF4G3) axis in lung squamous cell carcinomas." (PMID 36120308, 2022).
male infertility (3 papers, 2019 to 2024). The inability of the male to effect fertilization of an ovum after a specified period of unprotected intercourse. "This gene has elevated expression in testis in humans, rats, and mice, and EIF4G3 mutations can cause male infertility in mice." (PMID 31684869, 2019). "This is consistent with the fact that EIF4G3 mutations cause male infertility." (PMID 37176068, 2023).
gastric cancer (2 papers, 2022 to 2023). A primary or metastatic malignant neoplasm involving the stomach. "Circ-EIF4G3 may contribute to the progression of gastric cancer, lung cancer, and other malignancies." (PMID 36816047, 2023).
hepatocellular carcinoma (2 papers, 2017 to 2025). A malignant tumor that arises from hepatocytes. "Although EIF4E, EIF4G3, NUDT4, and NUDT11 expression levels did not exhibit a statistically significant differential between neoplastic and normal samples, their expression displayed an upward trend in hepatocellular carcinoma (HCC) tissues." (PMID 40485623, 2025).
lung carcinoma (2 papers, 2022 to 2023). "On the other hand, mutation status results showed that the top mutated genes such as EIF4G3, which was reported to silence EIF4G3, could induce cell apoptosis and suppress tumor growth in lung cancer cell lines." (PMID 36761423, 2022).
autism (1 paper, 2020). Persistent deficits in social interaction and communication and interaction as well as a markedly restricted repertoire of activity and interest as well as repetitive patterns of behavior. "MEs within the EIF4G1 and EIF4G3 transcripts were shown to be misregulated in autism patients and control synaptic translation and cognition contributing to pathogenesis of this condition." (PMID 33207694, 2020).
breast carcinoma (1 paper, 2022). "Among the identified potential NSCLC oncogenes, a reduction in the germline copy number of EIF4G3 is linked to breast cancer susceptibility in the Japanese population." (PMID 36499305, 2022).
cervical cancer (1 paper, 2024). A primary or metastatic malignant neoplasm involving the cervix. "Similarly, EIF4G3’s role in oncogenesis is underexplored, but this study establishes its relevance in cervical cancer progression." (PMID 40729294, 2024). "By identifying new factors such as SF3B1 and EIF4G3, which show increased mRNA expression and altered methylation patterns in cervical cancer and precursor lesions, the research underscores the potential of these genes as biomarkers for early detection and diagnostic precision." (PMID 40729294, 2024). "In this context, this study aimed to evaluate the potential of the investigated factors EIF4G3 and SF3B1, including the methylation status of CpG islands around gene promoters and their expression in cervical cancer and precursor lesions, and to assess their prognostic potential." (PMID 40729294, 2024).
colon carcinoma (1 paper, 2022). "As one example, 24 TSSs were annotated for EIF4G3, while only the proximal TSS was used in the colon carcinoma cell line (represented by CAGE-seq), which could be distinguished by our method." (PMID 36528241, 2022).
infertile (1 paper, 2021). "Deletion of Eif4g3 affects Hspa2 translation and inhibits sperm formation during the meiosis stage, leading to infertility." (PMID 34312369, 2021). "Among the proteins that interact with these proteins, the expression levels of Hspa2 and Eif4g3 proteins were significantly reduced in the infertile group because of Ubb-knockout as compared to that in WT mice." (PMID 34312369, 2021).
liver cancer (1 paper, 2023). An epithelial or non-epithelial malignant neoplasm that arises from the liver. "Among the genes associated with the prognosis of liver cancer, the genes associated with shorter survival period are AGO2, DCPS, IFIT5, LARP1, NCBP2, NUDT10, and NUDT16; the genes associated with longevity are EIF4E3, EIF4G3, METTL1, NCBP1, NSUN2, NUDT11, NUDT4, and WDR4." (PMID 36845384, 2023).
prostate carcinoma (1 paper, 2022). A carcinoma that arises from epithelial cells of the prostate gland. "Other than PTPN4, no statistical significance was found regarding EIF4G3 or UBE3A expression when prostate cancer tissues were compared to normal tissues in the UALCAN database." (PMID 36042375, 2022).
sarcoma (1 paper, 2023). A usually aggressive malignant neoplasm of the soft tissue or bone. "Risk score = (0.1472) *EIF4A1 + (0.4087)*EIF4G3 (−0.2538)*NCBP1 + (0.6578)*WDR4 was applied to the calculation of OS in sarcoma patients." (PMID 36816047, 2023). "TMB and MSI scores of sarcomas were dramatically enhanced with the increase of EIF4G3, NCBP1, and WDR4 expression according to our findings." (PMID 36816047, 2023). "Sarcoma patients were divided into two groups according to the risk scores, survival status, and the expression of EIF4A1, EIF4G3, NCBP1, and WDR4." (PMID 36816047, 2023). "Sarcoma patients were divided into two groups based on the distribution of risk scores, survival status, and expression of EIF4G3 and WDR4 and the risk score = (0.1036)*EIF4G3 + (0.5255)*WDR4 was applied to the calculation of DSS." (PMID 36816047, 2023). "Moreover, AGO2, EIF4G3, NCBP1, and WDR4 were potential risk factors for DSS in sarcomas." (PMID 36816047, 2023). "Theoretically, miRNAs that bind to high expression EIF4A1, EIF4G3, NCBP1, and WDR4 should be down regulated in sarcomas and show poor prognosis." (PMID 36816047, 2023). "The correlation between the expression of prognostic m7GRGs (EIF4A1, EIF4G3, NCBP1, WDR4) and immune infiltration in sarcomas was investigated using the TIMER database and TCGA database." (PMID 36816047, 2023). "Patients with sarcoma who had high levels of EIF4A1, EIF4G3, NCBP1, and WDR4 exhibited a lower OS rate." (PMID 36816047, 2023). "Besides, we constructed a prognostic model that consists of EIF4A1, EIF4G3, NCBP1, and WDR4 m7GRGs for predicting the survival likelihood of sarcoma patients." (PMID 36816047, 2023). "According to TIMER data, EIF4G3, and NCBP1 were negatively connected with CD4+ T cells and dendritic cells, however, EIF4A1 and WDR4 were not substantially correlated with immune cell infiltration in sarcomas." (PMID 36816047, 2023).
sterility (1 paper, 2019). "Fertility data for bucks, particularly F1 hybrids, will be key for testing whether there is an association between sterility and EIF4G3 genotypes in Odocoileus." (PMID 31684869, 2019).
tumor (13 papers, 2014 to 2025). "In this study, we identified circEIF4G3, a novel circRNA that was produced by backsplicing of EIF4G3 gene transcript, was downregulated in tumor tissues and serum of patients with GC." (PMID 35780119, 2022). "Subclone 11 contained EIF4G3, IL12RB2, and PDE4B mutations, and all three mutations had zero allele frequencies in the tumor sample P6_T11, indicating the possibility of secondary driver genes for this subclone." (PMID 34075047, 2021). "Silence of EIF4G3 also induced cell apoptosis and suppressed tumor growth in NCI-2170 and NCI-H226 cells." (PMID 34194495, 2021). "In addition, the scaffold protein EIF4G3 was identified as a direct target of miR-375 and the suppression of EIF4G3 induced cell apoptosis and inhibited tumor growth in NCI-2170 and NCI-H226 cells." (PMID 34194495, 2021). "Genes such as EIF4E3, IFIT5, EIF4G3, NUDT16, NUDT10, NCBP3, and NUDT11 showed lower expression in tumor tissues, whereas other genes were highly expressed." (PMID 41406096, 2025). "An elevated protein expression of EIF4E, EIF4G3, LARP1, METTL1, NCBP1, NUDT4, and NUDT11 was discerned in the carcinoma samples, whereas the WDR4 expression was comparable between the tumor and adjacent non‐tumorous tissues." (PMID 40485623, 2025). "Only EIF4E3, IFIT5, EIF4G3, NUDT16, NUDT10, NCBP3, and NUDT11 showed decreased expression in tumor tissues." (PMID 41406096, 2025). "The protein expressions of METTL1, NSUN2, EIF4G3, LARP1, NCBP1, and NCBP2 were higher in tumor tissues than in normal tissues; however, the protein expressions of WDR4, EIF4E1B, and NCBP2L were negative in both tumor and normal tissues." (PMID 35785179, 2022). "In conclusion, our results systematically explored the role of miR-375/EIF4G3 axis in chidamide-induced LSCC apoptosis and tumor growth arrest, which may afford an effective strategy to overcome the drug resistance of chidamide in clinical cancer therapy." (PMID 34194495, 2021).
cancer (12 papers, 2014 to 2025). A tumor composed of atypical neoplastic, often pleomorphic cells that invade other tissues. "Next, we added NuRD complex as a new molecule and ran the “Path Explorer” tool between SET A (NuRD) and SET B (SF3B1B, PHF6, EIF4G3, DCP2, GPR15, miR-490, LINC01222, LINC01718, LINC02036) with the same parameters for diseases: “Cancer”, “Infectious Disease”, and “Reproductive Disease System”." (PMID 38790189, 2024).
infection (5 papers, 2009 to 2017). The state of being infected such as from the introduction of a foreign agent such as serum, vaccine, antigenic substance or organism. "In the absence of GrB, eIF4G3 protein expression did not change significantly from 0 to 18 hr post infection, while GrB-dependent downregulation of viral protein expression correlated with a decrease in eIF4G3 levels." (PMID 22194691, 2011).
neurodegenerative disease (1 paper, 2025). A disorder of the central nervous system characterized by gradual and progressive loss of neural tissue and neurologic function. "Similarly, ankyrin repeat domain 30B like (ANKRD30BL, 2q21.2), catenin alpha 3 (CTNNA3, 10q21.3), and eukaryotic translation initiation factor 4 gamma 3 (EIF4G3, 1p36.12), all previously implicated in neurodegenerative diseases, were also found to undergo sex‐specific RNA editing." (PMID 40631452, 2025).
EIF4G3 also shares sentences with these, for which no sentence is quoted: cervical tumor (1 paper); diffuse large B-cell lymphoma (1); Hepatitis B (1); infectious disease (1); lymphoma (1); melanoma (1); mesothelioma (1); Reproductive Disease (1); viral infection (1).